TYRP1 (tyrosinase related protein 1)
Diseases named in the same sentence as TYRP1 in open-access papers (continued):
Sharing a sentence is not in itself a finding about the gene and the disease.
melanoma (continued). "This analysis further supports the notion that the TYRP1 transcript level is stable also in clinical samples of relapsed melanomas that are resistant to BRAFV600 and BRAFV600 + MEK1/2 inhibitors." (PMID 31624899, 2020). "TYRP1 mRNA is of interest due to its potential non-coding role as a sponge sequestering tumor-suppressive miRs in melanoma." (PMID 31624899, 2020). "Our findings are supported by the analysis of publicly available data on TYRP1 expression in melanoma samples from patients before treatment and at the time of tumor progression due to development of resistance to targeted therapeutics." (PMID 31624899, 2020). "For the first time, we showed that TYRP1 expression remained unaltered in melanoma cells that became resistant to vemurafenib or trametinib, including those cells losing MITF-M." (PMID 31624899, 2020). "This was well reflected at the protein level as TYRP1 protein was undetectable in BRAFV600E melanoma cells, whereas for RASQ61R cells a strong signal was obtained." (PMID 31624899, 2020). "It is possible that regulation of TYRP1 expression in MITF-Mlow melanoma cells is stabilized by other transcription factors or regulatory mechanisms." (PMID 31624899, 2020). "TYRP1 transcript levels stay unaltered in the majority of paired melanoma samples from patients before treatment and after relapse caused by resistance to targeted therapies." (PMID 31624899, 2020). "TYRP1 is an enzyme catalyzing the oxidation of dihydroxyindole carboxylic acid during the process of melanin biosynthesis in murine melanoma cells." (PMID 32707654, 2020). "Among the many enzymes involved, melanogenic enzymes present in melanocytes and melanoma cells, such as tyrosinase, tyrosinase-related protein 1 (TRP-1), and tyrosinase-related protein 2 (TRP-2), are the most important regulators of melanin biosynthesis." (PMID 31275396, 2019). "AIRE deficiency finds to decrease the expression of Tyrosinase Related Protein 1 (TYRP1) in thymus, yet increases the T cell immune responses against melanoma development." (PMID 31641374, 2019). "Another study also outlined the sequestration of an abundant miRNA, miR-16, by TYRP1 (tyrosinase-related protein 1) mRNA in melanoma." (PMID 29702599, 2018). "To this end, we isolated CD4+ T cells from TRP-1 mice, which express a MHC Class II-restricted, transgenic TCR specific for the tyrosinase-related protein 1 antigen present in melanoma." (PMID 30687308, 2018). "We proposed a method of shortened ex vivo expansion using Th17 cells to treat melanoma using the TRP-1 transgenic mouse model in which CD4+ T cells express a TCR that recognizes tyrosinase-related protein 1 on melanoma." (PMID 30400835, 2018). "Here, in addition, we describe a novel activity of the HSP90 inhibitor 17-AAG which induces melanization in BRAFWT melanoma cells in a tyrosinase-independent manner while increasing expression of accessory melanogenic enzymes and tumor antigens TYRP1 and DCT." (PMID 29481571, 2018). "In melanoma, TYRP1 (tyrosinase-related protein 1) RNA acts like a sponge which, when associated with miR-16, limits its tumor suppressor activity." (PMID 30349480, 2018). "In mouse melanoma cells miR-211 acts by increasing the mRNA and subsequently protein levels of Tyrosinase (Tyr) and Tyrosinase-Related Protein 1 (Tyrp1), two enzymes involved the biosynthesis of melanin pigment." (PMID 28445987, 2017). "Western blotting demonstrated that SASH1 mutations significantly increased TYRP1, Rab 27a, Pmel17 and tyrosinase protein levels in SK‐MEL‐28 cells, a pigmented melanoma cell line and NHEMs." (PMID 27885802, 2017). "Western blot analysis revealed that 10-HDA inhibited the activity of tyrosinase and the expression of tyrosinase-related protein 1 (TRP-1), TRP-2, and microphthalmia-associated transcription factor (MITF) in B16F1 melanoma cells." (PMID 28793915, 2017).
melanoma (continued). "Previously, we have shown that CD4+ T cells specific for a tumor-associated self-antigen (TAA) called tyrosinase-related protein 1 (TRP-1), a melanoma differentiation antigen (MDA), can treat large established tumors by direct killing of cancerous cells." (PMID 26981246, 2016). "The prooxidant state in melanoma induces alterations in proteins involved in melanogenesis, such as tyrosinase and TYRP1." (PMID 27206673, 2016). "The role of Aire in negative selection has also been studied in TCR-transgenic models where clonotypic T-cells are targeted toward naturally expressed self-antigens such as the melanocyte-/melanoma-specific tyrosinase-related protein-1 (TRP-1)." (PMID 24592265, 2014). "Additional pigmentation-related genes associated with melanoma risk are tyrosinase (TYR); tyrosinase-related protein 1 (TYRP1); solute carrier family 45, member 2 (SLC45A2); and solute carrier family 24, member 4 (SLC24A4)." (PMID 24392023, 2013). "In conclusion, we found that TYRP1 gene expression level in melanoma skin metastases correlates with both DMFS and OS and with Breslow thickness." (PMID 22045183, 2011). "Our data indicate that TYRP1 mRNA expression level, at least in skin metastases, is a prognostic marker for melanoma, and is particularly useful when prognostic pathology parameters at the primary lesion are lacking." (PMID 22045183, 2011). "This work describes a gene profiling study in skin and lymph nodes, which are the most frequent melanoma metastases, that shows an inverse correlation between tyrosinase-related protein 1 (TYRP1) expression level and patient overall survival." (PMID 22045183, 2011). "Recent GWAS have unveiled association between SNPs or genetic variants in MC1R, TPCN2, ASIP, KITLG, SLC24A5, TYR, IRF4, OCA2/HERC2, SLC24A4, SLC45A2, TYRP1, and pigmentation as well as melanoma." (PMID 21559390, 2011). "Tyrp1 is the most common melanoma antigen and Gpnmb is used as a marker for metastatic melanomas and has recently been identified as a potential molecular therapeutic target in patients with glioblastoma multiforme." (PMID 17608931, 2007). "Preclinical data suggest that monoclonal antibodies targeting TYRP1 confer anti-melanoma activity." (PMID 39943991, 2024). "Indeed, the three 20D7S-derived TYRP1 CARs are cytotoxic and secrete cytokines upon co-culture with the B16 murine melanoma cell line." (PMID 38336975, 2024). "Prevalence of TYRP1 expression differed between melanoma subtypes, with uveal melanoma showing the highest frequency of positive samples with any TYRP1 expression (91%, n = 41 of 45) followed by mucosal melanoma (74%, n = 20 of 27) and cutaneous melanoma (59%, n = 80 of 135)." (PMID 38577337, 2024). "In case study 3, we applied VIBE to analyze DEGs found by other tools, showing the expression of these genes and gene signatures across outcome groups and TCGA indications, thereby identifying TYRP1 as a potential target for melanoma patients who have progressed on nivolumab." (PMID 39943991, 2024). "Given the high expression of TYRP1 in biopsies from patients with acral, mucosal, and uveal melanoma, we tested the antitumor activity of the TYRP1 clinical candidate in models of these rare melanoma subtypes." (PMID 38336975, 2024). "We hypothesized that incorporation of TYRP1, a melanocyte differentiation antigen expressed in melanocytes and melanoma present in 65% of UM, may additionally upregulate an immune response to pigmented cells, thus improving immunogenicity." (PMID 38022659, 2023).
melanoma (continued). "To determine whether DGKi enhances suboptimal TCR signaling in effector CD8 T cells, we used both B16 melanoma cells and the pancreatic cancer cell line 6694c2 transduced to express low amounts of Tyrp1 (C2VTrp1)." (PMID 38000024, 2023). "While there were no clear objective responses to VSV-IFNβ-TYRP1, dose-dependent immunogenicity to melanoma antigens was seen, both to virus-encoded TYRP1 and other melanoma antigens (gp100, hTERT, and cyclin D1), suggesting epitope spreading." (PMID 38022659, 2023). "This discovery indicates TYRP1 as a possible prognostic marker for stage III melanoma patients." (PMID 36614156, 2022). "Here, we showed that removing immune suppression and enhancing stimulatory signals increased the anti-tumor activity of unmodified TA99 antibodies (anti-TYRP1) with a significant reduction of growth of solid tumors and lung metastases in mouse models of melanoma." (PMID 33520112, 2021). "TYRP1 protein expression is reduced in invasive melanomas, while TYRP1 mRNA level is increased." (PMID 31624899, 2020). "As TYRP1 mRNA level remains unaltered in melanoma cells during development of resistance to vemurafenib or trametinib, therapies developed to terminate a sponge activity of TYRP1 transcript may be extended to patients that relapse with resistant disease." (PMID 31624899, 2020). "The DEGs that associated with other genes in this network are KIT, CDKN1C, and TYRP1, suggesting these three DEGs may affect melanoma, in which TYRP1 was both a DEG and a melanoma gene." (PMID 32015692, 2020). "In the present study, a cohort of patients SPMs (n = 20) and MPMs (n = 19), sex-matched, was analyzed with our custom NGS panel that included 32 genes involved in melanoma susceptibility (e.g., CDKN2A, BAP1, POT1) and skin/hair pigmentation (e.g., TYR, TYRP1, OCA2)." (PMID 33748184, 2020). "It would be interesting to check whether there is any correlation between the molecular type of melanoma (mBRAF, mRAS, mNF1, or triple wild type) and TYRP1 expression." (PMID 31624899, 2020). "The prior identification of DCT and TYRP1 as melanoma tumor antigens prompted us to investigate whether melanoma cells became more immunogenic following 17-AAG exposure." (PMID 29481571, 2018). "In fact, TYRP1 expression is an intriguing feature: it has been reported that the transcription of TYRP1 is frequently and selectively attenuated and completely extinguished in melanoma cell lines." (PMID 29733692, 2018). "In previous studies, DCT and TYRP1 were identified as melanoma tumor antigens." (PMID 29481571, 2018). "First, we determined whether HSP90 inhibition by 17-AAG exhibited similar effects upon Tyrp1 and Dct expression in cultured B16 murine melanoma cells." (PMID 29481571, 2018). "It is unclear whether other common variants that have been associated with melanoma, particularly other pigmentation genes, such as SLC45A2, TYR or TYRP-1, may also exhibit a similar modifying effect CDKN2A penetrance similar to MC1R." (PMID 29774366, 2018). "We observed a significantly higher number of cells positive for TYRP1 in the trigenic group compared to the bigenic group with spontaneous melanomas, and a significant increase in TYRP1+ cells in LNs from the Rxrαep−/− mice compared to their RxrαL2/L2 controls post acute neonatal UVB exposure." (PMID 29121869, 2017). "There was a higher degree of malignancy in melanomas from the trigenic Rxrαep−/− mouse line, where we observed a higher number of TYRP1-expressing melanoma cells invading into draining lymph nodes in RXRαep−/−|Tyr-NRASQ61K|Cdk4R24C/R24C mice with increased drainage seen in the UVB treated mice." (PMID 29121869, 2017). "Therefore, considering that H2O2 inhibits TYR, TYRP1 and TYRP2, the high levels of H2O2 associated with low catalase activity in melanoma would be relevant in the induction of the amelanotic phenotype." (PMID 27206672, 2016).
melanoma (continued). "Moreover, as TYRP1 gene is related to pigmentation and is exclusively expressed in melanocytes and melanoma cells, the documented changes in its expression is restricted to tumour tissues." (PMID 22045183, 2011). "The expression levels of TYRP1 might have prognostic implications in melanoma." (PMID 41465475, 2025). "Similarly, we established a panel of four acral melanoma cell lines (SK-Mel709B, SK-Mel1094A, SK-Mel990A, and SK-Mel1107A), two of which presented high TYRP1 expression, in line with the frequency of TYRP1 overexpression observed in patient biopsies." (PMID 38336975, 2024). "Finally, we measured the TYRP1 protein level by immunohistochemistry in metastatic lesions of cutaneous (n = 11), acral (n = 10), mucosal (n = 6), and uveal (n = 11) melanoma and showed that a significant subset of the patients analyzed presented high and homogeneous TYRP1 expression." (PMID 38336975, 2024). "While TA99 alone resulted in a significant, but incomplete decrease in the number of nodules of lung metastases as measured by visual counts or Tyrp1 melanoma antigen measured by RT-PCR, Imprime alone did not cause a decrease in lung metastases or Tyrp1 expression." (PMID 35692755, 2022). "Thus, eliminating regulatory events (via antibody-mediated Treg depletion) or inducing activation of immune effectors (using anti-4-1BB agonistic mAb), enhanced the therapeutic effects of the TA99 anti-tumor monoclonal antibody (anti-TYRP1) in the B16 mouse model of melanoma." (PMID 33520112, 2021). "It would be interesting to explore if TYRP1 may contribute in the development of a melanoma-targeted therapy or drug delivery system, in as much as melanogenesis and TYRP1 are biological properties highly elevated and uniquely expressed in melanocytes and melanoma cells." (PMID 32854423, 2020). "Therefore, influence of miR-155 on the TYRP1 transcript stability might be diminished during melanoma development." (PMID 31624899, 2020). "However, despite the low number of neoantigens, UM expresses a couple of immunogenic antigens as melanoma antigen recognized by T cells (MART-1/Melan-A), glycoprotein 100 (gp100), tyrosinase, tyrosinase-related protein-1 (TRP-1), or melanoma-associated antigen (MAGE)." (PMID 32013269, 2020). "Hence we asked whether the combination of 17-AAG, responsible for induction of Tyrp1, and adoptive transfer of cytotoxic CD4+ T cells specific for Tyrp1 can enhance the anti-tumor immune response by delaying recurrence of B16 melanomas." (PMID 29481571, 2018). "The increase in PCNA+/TYRP1+ cells within the RXRαep−/−|Tyr-NRASQ61K|Cdk4R24C/R24C skin as compared to the RxrαL2/L2 control mice indicated the presence of a large volume of proliferating melanocytes in the mutant melanomas in absence or in presence of acute UVB." (PMID 29121869, 2017). "Indeed, the expression of TYRP1 was inversely correlated with tumor stage in malignant melanoma." (PMID 21647268, 2011). "A smaller tissue from patient ID 9561, collected in 2008, had four clusters, including melanoma (PMEL, TYRP1), immune cells (TMSB4X, IL32), keratinocytes (KRT10, KRT1, DSG1), and fibroblast areas (COL1A2, COL1A1, DCN)." (PMID 39846232, 2025). "In melanoma cells (B16 murine melanoma cell line), TYR is co-expressed with TYRP1 or TYRP2 under the regulation of MITF." (PMID 41515356, 2025). "To further confirm TYRP1 CAR selectivity, we assessed the cytotoxicity and cytokine release upon co-culture with a panel of non-melanoma TYRP1neg cell lines (A549 lung adenocarcinoma as well as UPS03 and UPS04 undifferentiated pleomorphic sarcoma)." (PMID 38336975, 2024). "Here, we identify Tyrosinase Related Protein 1 (TYRP1) as a CAR-T cell therapy target to treat patients with cutaneous and rare melanoma subtypes unresponsive to immune checkpoint blockade." (PMID 38336975, 2024). "For instance, TYRP1 transcript levels fluctuate independently of MITF in patient-derived melanoma cells and in the SK-MEL-19 human melanoma cell line." (PMID 39228400, 2024).
melanoma (continued). "Using patient-derived models of cutaneous, acral, and uveal melanoma, we showed the relevance of TYRP1 surface expression as a target for CAR-T cell therapy for cutaneous melanoma and rare melanoma subtypes in patients with high TYRP1 overexpression." (PMID 38336975, 2024). "RES reduced the expression of melanogenesis-related proteins, such as tyrosinase, tyrosinase-related protein 1 (TYRP1), TYRP2, and MITF in melanoma cells." (PMID 39337478, 2024). "A weekly combination therapy of anti-PD1, TA99-Neo2/15 and DLnano-vaccines against Gp100, Tyrp1, and Trp2 significantly improved survival in a therapeutic murine B16F10 melanoma model, inducing complete response in a subset of mice." (PMID 36911698, 2023). "Jineol also reduced melanin content in melanoma cells by downregulating MITF expression through interference with ERK1/2 and p38 phosphorylation and suppressing the protein levels of tyrosinase, tyrosinase-related protein 1 (TYRP-1) and TYRP-216." (PMID 36782003, 2023). "We also examined the transcription of melanin synthesis genes TYR, TYRP1, PMEL, MLANA and DCT by RNAseq analysis in M14 human melanoma cells in which we have disrupted TXNRD1 using Crispr/Cas9 (M14TXNRD1+/− cells)." (PMID 36291795, 2022). "In the B16 melanoma model, which has been characterized to be MHC class I-defective and highly refractory to ICIs, Imprime combined with the anti-Tyrp1 Ab TA99 almost completely prevented outgrowth of lung metastases." (PMID 35692755, 2022). "Immunostaining confirmed the expression of Melan-A, SRY-box transcription factor 10 (Sox10), human melanoma black-45 (HMB-45), and tyrosinase-related protein 1 (TRP1) (green) in all cultured CD90−CD117+ cells." (PMID 35269891, 2022). "Western blot analysis demonstrated that WFP reverse α-MSH induced melanogenesis in A375 melanoma cells, including in down-regulated TRY, TYRP-1, TYRP-2, MITF and CREB expressions." (PMID 35752787, 2022). "This transcription factor that promotes the expression of the most melanogenic proteins including TYR, TYRP1, DCT and PMEL, was found to be also critical for melanoma invasion and proliferation upon down-regulation in melanoma cells." (PMID 36776379, 2022). "It has been suggested that in human melanoma cells, CRH and urocortin regulate TYRP1 gene expression via NURR1/NUR77 production." (PMID 34884858, 2021). "Notably, eight of the nine UVR-exposed mucosal melanomas and all 51 UVR-exposed cutaneous melanomas carried mutations in one to eleven known melanoma genes, with the remaining mucosal melanoma (MuM10) carrying a frame-shift mutation in the melanocyte gene TYRP1." (PMID 33431815, 2021). "We and others demonstrated in melanoma that ASO strategy is feasible in vivo by targeting SAMMSON mRNA and the lncRNA TYRP1." (PMID 33724679, 2021). "In vitro experiments revealed that the knockdown of TYRP1 promoted the expression of MHC class I. TYRP1 correlated with the formation of melanogenesis and was a cancer antigen of melanoma." (PMID 33869027, 2021). "It is also known that daidzein and EQ 1 decrease the expression of tyrosinase, tyrosinase-related protein-1 (TRP-1), and tyrosinase-related protein-2 (TRP-2), thereby blocking melanin production in α-MSH-stimulated B16 melanoma cells." (PMID 34502054, 2021). "The miR-155-5p is highly expressed in melanoma patients and targets the 3′UTR region of TYRP1 (Tyrosinase Related Protein 1) mRNA in a SNP-dependent manner leading to decreased TYRP1 transcript levels." (PMID 34449663, 2021). "Western blot analyses showed that the protein levels of both TYRP-1 and CD63 were higher in melanosomes derived from GIF-2209-treated B16F10 melanoma cells." (PMID 35011407, 2021). "L-Cysteinamide inhibited TYR-mediated dopachrome formation in vitro and eumelanin synthesis without altering the mRNA and protein expression levels of TYR, TYRP1, and DCT in darkly pigmented human melanoma MNT-1 cells and/or normal HEMs." (PMID 34439449, 2021).